BRAF (B-Raf proto-oncogene, serine/threonine kinase)
Diseases named in the same sentence as BRAF in open-access papers (continued):
Sharing a sentence is not in itself a finding about the gene and the disease.
melanoma (continued). "Whether to give targeted therapy or immunotherapy first to patients with BRAF mutant melanoma remains an important clinical question." (PMID 24743024, 2014). "Notably, the majority of these truncation mutations co-occur with BRAF and NRAS mutations, suggesting a potential cooperating role during the progression of melanoma." (PMID 25393105, 2014). "The BRAF inhibitor, vemurafenib, suppressed melanoma cell growth in a TRIM16-dependent manner." (PMID 25333256, 2014). "For example, targeting a BRAF mutation in melanoma is not the same as targeting the same mutation in colorectal cancer." (PMID 25401499, 2014). "Despite the initial success of some molecular targeted therapeutics in melanoma, there remains a great need for other therapeutic agents that act in a manner independent of BRAF mutational status." (PMID 25057921, 2014). "They found the translocation in 78.6% of the CCSs but in none of the melanomas, whereas BRAF and NRAS mutations were present in, respectively, 51.6 and 12.9% of the melanomas and not in any of the CCSs." (PMID 25593912, 2014). "In this scenario, the lessons learned from metronomic treatment strategies for BRAF V600E melanomas as well as EGFR-mutant NSCLCs suggest that discontinuous dosing of the drug could be a strategy to prevent or retard acquired resistance." (PMID 24811491, 2014). "The combined inhibition of BRAF and MEK is hypothesised to improve clinical outcomes in patients with melanoma by preventing or delaying the onset of resistance observed with BRAF inhibitors alone." (PMID 25374620, 2014). "Treatment of BRAF mutant melanomas with specific BRAF inhibitors leads to tumor remission." (PMID 25538140, 2014). "As seen in melanoma patients, resistance to BRAF inhibitors such as PLX4032 could occur in thyroid cancer patients as well." (PMID 24673746, 2014). "Next, we studied this in a BRAF-mutant murine model of melanoma." (PMID 25941608, 2014). "Recently, BRAF mutant melanoma samples were distinguished from BRAF wild-type samples, suggesting that gene expression profiling according to BRAF status might be useful for the identification of molecular markers involved in RAS-RAS-MEK-ERK-MAPK signalling." (PMID 25361007, 2014). "While frequency rates of BRAF mutations were quite identical across the different MPM lesions, a significant increase of cKIT (p < 0.001) and CyclinD1 (p = 0.002) amplification rates was observed between first and subsequent primary melanomas." (PMID 24885594, 2014). "BRAF inhibitor resistance could be caused by HGF-triggered MET activation, and IGF-1 triggered its receptor activation in BRAF mutant melanoma." (PMID 24952482, 2014). "Mutations in BRAF, the downstream effector of KRAS are reported in up to 70% of melanoma cancer cell lines and they are highly prevalent in most common cancers with poor prognosis such as malignant melanoma." (PMID 25361007, 2014). "The role of CREB in regulation of Noxa by MEK/ERK signaling was further confirmed by its association with the Noxa promoter in melanoma cells regardless of their BRAF mutational status as shown by chromatin immunoprecipitation (ChIP) assays." (PMID 25365078, 2014). "Selective inhibitors of the kinases BRAF and MEK for the treatment of patients with otherwise refractory BRAF mutant melanoma have demonstrated impressive efficacy, and combination treatment with these agents may prove to be even more effective." (PMID 25031620, 2014). "So far, only few melanoma patients were enrolled in this study, and it is too early to state whether the dual inhibition strategy is more successful than BRAF inhibitor monotherapy." (PMID 24970815, 2014). "The patient population was typical for patients with BRAF-mutant metastatic melanoma; the median age of patients was 51 years, 54% of patients were men, 85% of patients had the V600E genotype, and 58% of patients had stage M1c melanoma." (PMID 24400126, 2014).
melanoma (continued). "Regarding the possible effects of metabolic preferences of melanoma tumors on the efficacy of targeted therapy, it is of interest that mutant BRAF inhibition might be more efficacious in tumors with higher glycolytic index." (PMID 24743024, 2014). "Our clinical observation indicates that in melanoma patients who developed resistance to selective BRAF inhibitors, rechallenge after treatment interruption might be beneficial." (PMID 25501056, 2014). "BRAF and NRAS genes typically show a mutually exclusive mutation pattern in melanoma samples." (PMID 24516372, 2014). "This study sought to determine whether levels of Wnt/β-catenin signaling in melanoma tumors prior to treatment might predict patient responses to BRAF inhibitors (BRAFi)." (PMID 24733413, 2014). "The detection of at least 1 mitosis/mm2 was associated with mutant BRAF in the entire cohort of patients (p = 0.038) and in patients with a tumor thickness of more than 1 mm (p = 0.046) but not in those with thin primary melanomas (p = 1.000)." (PMID 24475086, 2014). "Lastly PDGFRα up-regulation has therapeutic implications since BRAF(V600E) melanoma patients with PDGFRα up-regulation may potentially benefit from treatment with BRAF-I in combination with PDGFRα-I or Shh-I." (PMID 24732172, 2014). "Mutations in BRAF alone do not induce melanoma, and the high frequency of BRAF mutations in benign nevi supports this conclusion." (PMID 24743024, 2014). "Using cell proliferation and DNA methylation assays, FACS analysis and quantitative-RT-PCR we have characterised the response of a panel of NRAS and BRAF mutant melanoma cell lines to various chemotherapy drugs, amongst them dacarbazine (DTIC) and temozolomide (TMZ) and DNA synthesis inhibitors." (PMID 24941944, 2014). "The difference in DMFS according to the BRAF mutational status was also limited to patients with tumor thickness of 1 mm or smaller (p = 0.011) and not evident in those with thicker primary melanomas (p = 0.745)." (PMID 24475086, 2014). "This cell line has the BRAF V600E, which is found in a large proportion of melanomas." (PMID 24919932, 2014). "Interestingly, a genetic abnormality in one melanoma patient was the NRAS mutation, whereas the other two patients harbored the BRAF V600E mutation." (PMID 25422890, 2014). "A small subset of melanomas that have no mutations in the major driver oncogenes were found to harbor BRAF fusions involving other genes." (PMID 24743024, 2014). "The important role of BRAF alternations in melanoma development is proven; however, the mutation itself is not sufficient for malignant transformation, and BRAF mutations also occur with high frequency in benign nevi." (PMID 24866436, 2014). "In melanoma mutant BRAF activates the NFκB signaling pathway." (PMID 24466036, 2014). "The RAC1P29S mutation was less frequent, but not mutually exclusive, in NRAS or BRAF mutated melanomas (6.2% vs 12.5%)." (PMID 25344914, 2014). "The use of Imatinib, for chronic myeloid leukemia and other solid tumors, of Trastuzumab and Lapatinib, for ERBB2 positive breast cancer, and of Vemurafenib, for BRAF mutant melanomas, are emblematic examples of how genomic alterations can be used to target cancer cells." (PMID 25193853, 2014). "Although upregulation and spliced variants of BRAF are often reported in drug-resistant melanoma models 7,22, we did not detect the aberrant expression of BRAF, excluding the possibility of BRAF expression-related resistance." (PMID 24634165, 2014). "Our results demonstrate that in melanoma the presence of mutually exclusive BRAF and NRAS mutations has no influence on the response to DNA alkylating agents such as TMZ." (PMID 24941944, 2014). "A number of subsequent reports have confirmed that inhibition of mutant BRAF could potentiate immune responses in melanoma, suggesting that blockade of immune checkpoints in combination with BRAF inhibitors could have clinical value." (PMID 24743024, 2014).
melanoma (continued). "Such study opened a new scenario on the possibility to combine highly effective targeted-therapies in the field of melanoma such as combinations of BRAF inhibitors, MEK inhibitors, and PI3K inhibitors with the optimal delivery of the drugs also in difficult to reach sites such as brain metastasis." (PMID 25101298, 2014). "In their subsequent studies the authors used gain-of-function and loss-of-function approaches to demonstrate that MITF is capable of cooperating with mutant BRAF to transform normal cells and that MITF knockdown causes loss of viability in MITF copy-gain melanoma cells." (PMID 24904423, 2014). "Somatic mutations in BRAF have been found in almost 50% of all melanomas and most commonly in melanomas derived from skin without chronic sun-induced damage." (PMID 24591764, 2014). "We have not found significant correlation between mutational status (BRAF/NRAS) and OS; however, for BRAF or NRAS mutated melanomas we observed significantly shorter disease-free survival (DFS) when compared with wild-type melanoma patients (p = .04; 5-year DFS, 18 vs 19 vs 31 %, respectively)." (PMID 24866436, 2014). "The BRAF inhibitor vemurafenib, approved for melanoma, is of limited use in NSCLC with BRAF mutations other than V600E, but might be of value in tumors with V600E mutations." (PMID 24722523, 2014). "The cobas 4800 BRAF V600 Mutation Test is the FDA-approved companion test for the qualitative detection of BRAFV600E mutation in DNA extracted from formalin-fixed, paraffin-embedded human melanoma tissue." (PMID 26328215, 2014). "BRAF inhibitors such as vemurafenib or dabrafenib efficiently block signaling downstream of the mutated BRAFV600 protein, which initially results in profound growth inhibition of the melanoma cells and high frequency of tumor regression in the clinic." (PMID 24735930, 2014). "Notably, recent trials (e.g. in melanoma) indicate that pharmacological interference using second-generation BRAF inhibitors produces sustained tumor regressions." (PMID 24938183, 2014). "Since Noxa is downregulated by BRAF inhibitors in mutant BRAF melanoma cells, we tested whether activation of MEK/ERK signaling is essential for constitutive expression of Noxa in the cells." (PMID 25365078, 2014). "Overall, slightly less than half of melanomas carry activating mutations in the BRAF gene, regardless of the mutation screening approach used." (PMID 24885594, 2014). "Moreover, the finding of higher plasma levels of circulating HGF in BRAF mutant melanoma patients suggested a trend toward a worse prognosis for these patients." (PMID 28548075, 2014). "There is strong rationale for combined BRAF-targeted therapy and immunotherapy for melanoma." (PMID 25344914, 2014). "Furthermore, we detail the changes in expression of several key regulators of apoptosis in BRAF-mutant melanoma in the setting of BRAF inhibition." (PMID 24983357, 2014). "Interestingly, treatment with BRAF inhibitors has demonstrated surprising effects on tumor antigen expression in the context of melanoma." (PMID 29250602, 2014). "In BRAF-mutant melanoma sustained mTORC1 signaling could be driven by alternative mechanisms of ERK activation or concomitant activation of the PI3K-Akt pathway, thus promoting resistance to RAF and MEK inhibitors." (PMID 24743024, 2014). "This suggests that combined treatment with a ROCK inhibitor and a BRAF inhibitor may be beneficial for patients with BRAF mutant melanoma." (PMID 25538140, 2014). "In addition, metformin can accelerate the growth of BRAF V600E-driven melanoma by upregulating VEGF-A and promote the angiogenic phenotype in the ERalpha negative MDA-MB-435 breast cancer model." (PMID 24849329, 2014). "The observation that all in situ melanomas were BRAF wild type is intriguing." (PMID 25526463, 2014).
melanoma (continued). "Further in vitro studies have been performed after the development of specific BRAF inhibitors, and BRAF inhibition in BRAF mutant melanoma cell lines and fresh tumor digests has been demonstrated to result in up regulation (up to 100-fold) of melanoma differentiation antigens." (PMID 25610709, 2014). "Additionally, we have chosen not to focus on BCL2A1, a recently described melanoma oncogene and mediator of BRAF inhibitor resistance in a subset of melanomas, as this was the subject of an independent analysis in our program." (PMID 24983357, 2014). "Interestingly, we found that treatment of melanoma cells with the BRAF inhibitor, vemurafenib, which attenuated ERK phosphorylation, resulted in increased levels of TRIM16 protein in vitro and in vivo." (PMID 25333256, 2014). "A CRISPR-Cas9 knock-out screening identified additional candidate genes whose ablation conferred resistance to BRAF inhibitor in melanoma cell line, including neurofibromin 2 (NF2), Cullin 3 E3 ligase (CUL3), and members of the STAGA histone acetyltransferase complex (TADA1 and TADA2B)." (PMID 24743024, 2014). "The identification ofstroma-mediated resistance in BRAF-mutant melanomas, through the secretion of hepatocytegrowth factor (HGF), therefore indicates a potential therapeutic strategy throughcombination treatment of RAF inhibitors and inhibition of the HGF activated pathway." (PMID 25490933, 2014). "Already we know that the emergence of resistance to the gene BRAF-targeted anti-melanoma drug Zelboraf frequently results from driver pathway cross talk, as does resistance to the targeted drugs Iressa and Tarceva when they are deployed against EGFR-driven lung cancers." (PMID 23303309, 2013). "Three melanoma cell lines were tested: M257 wild-type BRAF, LCP BRAFV600R and WM266 BRAFV600D." (PMID 23317446, 2013). "The V600E mutation in BRAF has now been associated with approximately 80% of melanomas and seen predominantly in melanomas arising on skin without chronic sun damage." (PMID 24220097, 2013). "Interestingly, inhibition profiles obtained with ex-vivo vemurafenib revealed a panel of 40 kinase substrates distinguishing the BRAF wild-type and BRAF(V600E) melanoma tumors." (PMID 24023633, 2013). "If this applies in vivo, then a proportion of melanoma patients whose disease is resistant to BRAF inhibitor therapy may respond to therapy with a MEK inhibitor." (PMID 23658559, 2013). "Our results indicate that GNAQ and BRAF activation drive distinct intracellular signalling pathways that may be useful for therapeutic decisions in human melanomas." (PMID 23904987, 2013). "The BRAF-MAPK axis may be a common attractive target for melanoma treatment, including immunotherapy." (PMID 23755373, 2013). "Summary of BRAF, NRAS, and GNAQ mutational status in melanoma cell lines." (PMID 23904987, 2013). "To determine whether depletion of PKN1 can further activate β-catenin signaling elicited by WNT3A and BRAF inhibitor (BRAFi) in melanoma, we transfected A375 cells harboring BAR with siRNAs targeting PKN1 or control duplexes." (PMID 24114839, 2013). "Ongoing clinical studies suggest limited activity of BRAF inhibitors in melanoma brain metastases." (PMID 24133630, 2013). "For example, targeting oncogenic BRAF with PLX4720 or PLX4032 resulted in inhibition of growth and invasion of 3D spheroids and caused tumor regression of melanoma xenografts, which was mirrored in phase II and phase III patient trials and has finally lead FDA-approval of vemurafenib." (PMID 27429258, 2013). "Finally, sequence analysis of the exon 4 and 5 of GNAQ gene, whose mutations have been associated with wild type BRAF and NRAS melanomas, revealed wild type status in all samples." (PMID 24238212, 2013). "However, in four pairs a BRAF-wildtype nevus was present next to a BRAFV600E-mutant melanoma; in five cases a BRAF-wildtype melanoma had a preexisting BRAFV600E-mutated nevus." (PMID 23861977, 2013).
melanoma (continued). "The phosphorylation patterns in melanoma did however not correlate to any clinical or molecular parameters, like BRAF- and NRAS mutational status, or response to DTIC therapy." (PMID 24023633, 2013). "Melanoma cell death induced by BRAF inhibitors may lead to release of multiple endogenous tumor antigens including mutated antigens unique to each patient (Melanoma is known to have more frequent mutations than other cancers probably due to UV irradiation)." (PMID 23755373, 2013). "Suppression of melanoma cell proliferation and invasion may also enhance total anti-tumor activity of mutant BRAF inhibitors." (PMID 23755373, 2013). "Elevated RAS/RAF signalling due to oncogenic mutations in BRAF or NRAS is well studied in melanoma, but these mutations are also common in non-proliferating senescent nevi." (PMID 23666755, 2013). "We also found that inhibition of MAPK signaling pathway in human melanoma cells by genetic depletion of mutant BRAF or specific inhibitors reduced production of multiple immunosuppressive cytokines such as IL-6, IL-10, and VEGF, in most cases without affecting cell viability." (PMID 23755373, 2013). "This variability in sensitivity towards vemurafenib has previously been observed in several melanoma cell lines, where the presence of BRAF mutations did not guarantee a response." (PMID 24023633, 2013). "Notably, BRAF and NRAS mutations are mutually exclusive in melanoma, which is also observed in our study." (PMID 24023633, 2013). "Taken together, these results indicate that cotreatment with HDAC and BRAF inhibitors can bypass canonical cell death pathways to kill melanoma cells, which may be of therapeutic advantage in the treatment of melanoma." (PMID 23744355, 2013). "Further analysis revealed that BRAF inhibitor did not cause cell death in melanoma of transgenic mouse model, suggesting that in situ destruction of cancer cells is an essential step in the enhancement of anti-tumor T cell responses." (PMID 23755373, 2013). "NRAS mutant melanoma is mutually exclusive of BRAF mutant melanoma." (PMID 24216705, 2013). "This patient received dacarbazine for MM discovered on bones metastasis during several months because of BRAF wild type status (both by IHC and molecular techniques) while the primary melanoma was unknown." (PMID 23976959, 2013). "The French platforms performed 3,479 BRAF tests on melanoma samples in 2011 and 4,629 in 2012." (PMID 24119386, 2013). "Consistent with their high mitochondrial metabolism, vemurafenib-resistant cells were more sensitive than parental cells to the lethal effect of the complex IV inhibitor, KCN suggesting that melanoma resistant to BRAF inhibitors largely depend on mitochondrial metabolism for survival." (PMID 24161908, 2013). "The observation of normal serum levels for both markers in patients who are in need for systemic therapy could be of clinical value especially in those with BRAF V600-mutant melanoma." (PMID 24312329, 2013). "Thus, HGF treatment restored growth inhibition of epidermal growth factor receptor (EGFR)-mutant lung carcinoma cells by the EGFR tyrosine kinase inhibitor gefitinib and that of BRAF-mutant melanoma cells by the BRAF inhibitors PLX4720 and PLX4032." (PMID 24216702, 2013). "A mutation may play different roles in different cancer types (e.g., BRAF V600 in colon cancer and melanoma)." (PMID 24205039, 2013). "We found that both the BRAF-mutated 1205Lu and NRAS-mutated WM1366 melanoma cell lines retain their sensitivity to dinaciclib when grown as 3D collagen-implanted spheroids, suggesting that modulating the tumor microenvironmental conditions does not increase resistance to this compound." (PMID 23527225, 2013).